TRPA1 (transient receptor potential cation channel subfamily A member 1)
Diseases named in the same sentence as TRPA1 in open-access papers (continued):
Sharing a sentence is not in itself a finding about the gene and the disease.
bone cancer (8 papers, 2010 to 2025). A primary or metastatic malignant neoplasm affecting the bone or articular cartilage. "TRPA1 are upregulated in rats with bone cancer pain, where they have been implicated in the pathways leading to neuropathic pain." (PMID 39940997, 2025). "TRPA1 are also of significant interest for their role in metastasis and overexpression in bone cancer, such as osteosarcoma." (PMID 39940997, 2025). "Macrophage-derived ROS has been shown to activate TRPA1 expressed in sensory neurons to elicit pain under several chronic pain conditions, including bone cancer pain, complex regional pain syndrome, neuropathic pain and fibromyalgia 79, 84-87." (PMID 39267790, 2024). "Injection of PTX (TNF-α synthesis inhibitor, pentoxifylline) and TRPA1 modulation attenuated mechanical and thermal hypersensitivity induced by bone cancer." (PMID 38940936, 2024). "This study mainly verified the role of TRPA1 in bone cancer transmission by antagonizing and knocking down TRPA1 expression." (PMID 35295475, 2021). "For instance, the up-regulation of tumour necrosis factor-α (TNF-α) and interleukin-6 (IL-6) in bone metastases may activate TRPA1 in the sensory neurons of bone cancer rats and contribute to CIBP." (PMID 39940997, 2025). "Whether TRPA1 also participates in bone cancer pain is unknown, but will be investigated in our further research." (PMID 20422007, 2010). "The boosted expression of TRPA1-, TRPV1-, and TRPV4-immunoreactive cells in ipsilateral L4–5 DRG due to bone cancer proliferation was inhibited by LTTL gel application." (PMID 38730655, 2024). "Among them, BDNF and TNF produced in bone tumor metastasis metabolism-α, MCP-1 and CCR2 can activate TRPA1." (PMID 35295475, 2021). "Both inflammatory cytokines TNF (α) and IL6 regulate bone cancer pain via TRPA1, but no data have proven the relationship between TRPA1 and tumours." (PMID 39770499, 2024).
heart failure (8 papers, 2014 to 2025). Inability of the heart to pump blood at an adequate rate to meet tissue metabolic requirements. "According to these studies, TRPA1 appears to play a role in regulating cardiac function under various conditions including heart failure." (PMID 33458442, 2021). "And, TRPA1 channel plays an important role on cardiovascular diseases such as heart failure and myocardial fibrosis." (PMID 33458442, 2021). "The role of TRPA1 in the formation of heart failure and myocardial fibrosis is difficult to determine, and further experimental proof is needed." (PMID 32903613, 2020). "To further investigate the potential mechanisms behind TRPA1-mediated Dox-induced cardiotoxicity in the heart, we examined the level of ER stress that plays a pivotal role in the development of heart failure." (PMID 29682158, 2018). "This may suggest that TRPA1 is involved in the regulation of heart failure through a Ca2+-dependent mechanism." (PMID 32903613, 2020). "The current research results indicate that activation of the TRPA1 channel does not cause an increase in sympathetic reflex under heart failure." (PMID 32903613, 2020). "In addition, TRPA1 inhibition significantly reduced critical factors involved in heart failure, including calcineurin and CaMKII phosphorylation in mice induced by pressure overload." (PMID 31680989, 2019). "Based on these studies, it may be suggested that TRPA1 participates in the regulation of heart failure via a Ca2+-dependent mechanism." (PMID 31680989, 2019).
Myocardial fibrosis (8 papers, 2019 to 2025). "In conclusion, the collective findings from these studies highlight the significance of TRPA1 modulation in myocardial fibrosis and associated cardiac dysfunction." (PMID 39323758, 2024). "It has been shown that TRPA1 stimulation causes macrophages to differentiate towards the M2 phenotype, thereby accelerating the infiltration of M2 macrophages in the heart, which exacerbates pressure-overload-induced myocardial fibrosis." (PMID 40149710, 2025). "Likewise, TRPA1 deficiency accelerated cardiac dysfunction and myocardial fibrosis in a transgenic mouse model of diabetes-induced dilated cardiomyopathy and in aged mice." (PMID 40149710, 2025). "The identification of calcium-dependent signaling pathways and M2 macrophage transition as mechanisms underlying the protective effects of TRPA1 inhibition provides valuable insights into the complex molecular pathways involved in myocardial fibrosis regulation." (PMID 39323758, 2024). "Their findings suggest that TRPA1 inhibition may represent a promising therapeutic strategy for mitigating myocardial fibrosis in diabetic patients, potentially reducing the risk of congestive heart failure, and improving overall cardiac function." (PMID 39323758, 2024). "In addition, inhibition of TRPA1 activity can significantly improve the degree of cardiac hypertrophy and myocardial fibrosis in mice, which may be related to weight loss and increase in aortic cross-sectional area." (PMID 32903613, 2020). "TRPA1 is expressed in cardiac fibroblasts from multiple species, and the role of TRPA1-mediated Ca2+ signals in myocardial fibrosis is still controversial." (PMID 40149710, 2025). "Studies utilizing animal models and experimental approaches have provided valuable insights into the potential therapeutic implications of targeting TRPA1 in the context of myocardial fibrosis." (PMID 39323758, 2024). "Recent research has shed light on the role of TRPA1 channels in modulating myocardial fibrosis and cardiac dysfunction in response to different pathological stimuli." (PMID 39323758, 2024). "In doxorubicin-induced dilated cardiomyopathy rat model, activation of TRPA1 using its agonist cinnamaldehyde alleviated cardiac dysfunction and fibrosis, suggesting a protective role of TRPA1 in myocardial fibrosis and dilated cardiomyopathy." (PMID 39323758, 2024). "The exacerbation of myocardial fibrosis and ventricular dysfunction in older Trpa1−/− mice suggests a protective role of TRPA1 against age-related cardiac pathology." (PMID 39323758, 2024). "Targeting TRPA1 signaling pathways holds promise for developing novel therapeutic interventions aimed at preventing or mitigating myocardial fibrosis-related cardiovascular complications." (PMID 39323758, 2024). "The findings indicate that knocking out Trpa1 accelerated myocardial fibrosis, ventricular dilation, and cardiac dysfunction." (PMID 36103570, 2022). "Some studies have shown that inhibition of TRPA1 reduces myocardial fibrosis induced by pressure overload." (PMID 36278189, 2022). "Taken together, we found that knocking out Trpa1 accelerated age-related myocardial fibrosis, ventricular dilation, and cardiac dysfunction." (PMID 36103570, 2022). "We found that knockout of Trpa1 exacerbated age-related myocardial fibrosis, ventricular dilation, and cardiac dysfunction in 52-week-old older mice." (PMID 36103570, 2022). "This indicates that TRPA1 activation has potential benefits in inhibiting TGF-β1-induced myocardial fibrosis." (PMID 32903613, 2020). "At least it is clear that TRPA1 plays an important role in the pathological process of myocardial fibrosis." (PMID 32903613, 2020). "Further research should be done to consider the role of TRPA1 in different stages of myocardial fibrosis formation and use this potential therapeutic target more accurately." (PMID 32903613, 2020).
Myocardial fibrosis (continued). "The present study using a Trpa1-/- mouse model provides evidence that TRPA1 may play a protective role in age-related myocardial fibrosis, ventricular dilation, and cardiac dysfunction." (PMID 36103570, 2022). "Moreover, some studies found that TRPA1 is also involved in the process of oxidative stress and myocardial fibrosis." (PMID 32903613, 2020). "For instance, Wang and coworkers showed that blocking TRPA1 with the selective inhibitors, HC-030031 and TCS-5861528, inhibited pressure overload-induced myocardial fibrosis by preventing the Ca2+-dependent recruitment of calcineurin and CaMKII." (PMID 40149710, 2025). "TRPA1 promotes the secretion of CGRP under the action of agonists and then inhibit the formation of myocardial fibrosis." (PMID 32903613, 2020).
Pain (8 papers, 2008 to 2025). An unpleasant sensory and emotional experience associated with actual or potential tissue damage, or described in terms of such damage. "Genetic deletion of TRPA1, or the blockade of its activation with a selective antagonist, abrogated trigeminal neuropathic pain and oxidative stress." (PMID 29682158, 2018). "The antiallodynic activity of cebranopadol (and morphine) in the oxaliplatin model of neuropathic pain, in particular in the acute phase, together with the results obtained in the formalin test indicate that both drugs tested are able to attenuate TRPA1-mediated pain responses in mice." (PMID 29071457, 2018). "Further, the research findings indicate that sodium, potassium, and calcium ion channels, in conjunction with diverse transient receptor potential families (e.g., TRPA1, TRPM8, and TRPV1), play a pivotal role in the pathophysiology of oxaliplatin-induced neuropathic pain." (PMID 40649805, 2025).
Stroke (8 papers, 2018 to 2024). Sudden impairment of blood flow to a part of the brain due to occlusion or rupture of an artery to the brain. "In patients with oropharyngeal dysphagia associated with aging, stroke, or neurodegenerative diseases, the latency to evoke a cortical response to pharyngeal electrical stimulation is reduced during the acute ingestion of TRPA1 agonists." (PMID 32867366, 2020). "We now provide good evidence that TRPA1 continues to be expressed into adulthood by presenting data from the TRPA1‐eGFP mice and this finding supports reports of TRPA1 block protecting myelin in in vivo models of stroke." (PMID 36762504, 2023). "Intriguingly, it has been shown that hypoxia-induced ROS lead to TRPA1 activation in mouse cerebrovascular endothelial cells and the ensuing TRPA1-mediated vasodilation contributes to halt ischemic damage after stroke." (PMID 34575985, 2021). "Future studies will assess whether drugs that activate TRPA1 have the potential to help reduce long-term disabilities in human patients who have a stroke." (PMID 30239332, 2018). "Furthermore, injecting normal mice experiencing a stroke with a drug that activates TRPA1 reduced the amount of damage to the brain." (PMID 30239332, 2018). "However, initial evidence suggests that TRPA1 activation on capillaries may induce vasodilation of arterioles and protect against widespread damage during stroke." (PMID 34577609, 2021). "In line with that, we find here that TRPA1 inhibition is beneficial at protecting against white matter damage when applied during, after, or throughout the ischaemic insult, suggesting that TRPA1 block may be used as a potential prophylactic therapy, or one to improve recovery after a stroke." (PMID 34577609, 2021).
airway hyperresponsiveness (7 papers, 2021 to 2025). "Concurrently, oxidative stress upregulates transient receptor potential vanilloid 1 (TRPV1) and transient receptor potential ankyrin 1 (TRPA1) channels, triggering neurogenic inflammation and airway hyperresponsiveness." (PMID 41450494, 2025). "Furthermore, the airway epithelium, including fibroblasts and smooth muscle cells, functionally expresses TRPA1, which mediates airway narrowing by mobilizing intracellular and extracellular Ca2+, thereby inducing airway hyperresponsiveness." (PMID 40678720, 2025). "Meanwhile, it was speculated that berberine could suppress TRPA1 to mitigate the inflammatory response and resolve airway hyperresponsiveness." (PMID 35586690, 2022). "However, it has been shown that relief of airway inflammation and airway hyperresponsiveness could be successfully achieved using a specific TRPA1 inhibitor (HC-030031)." (PMID 35586690, 2022). "The development of TRPA1 antagonists, such as BI01305834 and GDC-0334, has demonstrated efficacy in preventing airway hyperresponsiveness, bronchoconstriction, and abnormal colorectal contractions." (PMID 39022308, 2024). "We conclude that TRPA1 is likely an important link between CS/CSE exposure and airway hyperresponsiveness, and speculate that acute CS/CSE-induced Ca2+ influx could lead to exacerbated ASM contraction and potentially initiate further chronic pathological effects of tobacco smoke." (PMID 33953304, 2021).
Allergy (7 papers, 2015 to 2026). An allergy is an immune response or reaction to substances that are usually not harmful. "Recent studies have linked TRPA1 to several disorders, including chronic pain, inflammatory diseases, allergies, and respiratory problems, owing to its activation by environmental toxins." (PMID 39273183, 2024). "The interaction between TDI and TRPA1 presents an intriguing pathology suggesting a role in allergic disease." (PMID 36877675, 2023). "This molecule enhanced TRPA1 responsiveness and, in turn, drove nociceptor-mediated neutrophil recruitment, revealing a novel mechanism by which lung-innervating neurons respond to air pollution in the context of allergy." (PMID 39229121, 2025). "For example, TRPA1 activation is considered important in the immune response, so it may be closely related to allergies and other immune-related diseases." (PMID 39273183, 2024). "A possible link between histamine and TRPA1 signaling might be thymic stromal lymphopoietin (TSLP), a known progressor of allergic diseases." (PMID 34439832, 2021).
overactive bladder (7 papers, 2016 to 2026). Symptom of overactive detrusor muscle of the urinary bladder that contracts with abnormally high frequency and urgency. "The activation of TRPA1 channel is implicated in hyper-reflexic micturition similar to overactive bladder." (PMID 27315798, 2016). "The effective blockade of TRPA1 with HC-030031 efficiently mitigated MGO-induced overactive bladder and detrusor hyperactivity." (PMID 38143915, 2023). "In previous studies, we found that intravesical injection of TRPA1 agonists induced hyper-reflexic micturition similar to overactive bladder." (PMID 27315798, 2016). "Importantly, these MGO-induced cystometric alterations were all reversed by intravesical infusion of HC-030031, indicating that TRPA1 activation in the urothelium plays a role in the machinery leading to overactive bladder." (PMID 38143915, 2023). "In addition to inflammation-induced models of LUTS, TRPA1 was also found to be upregulated in L6-S1 DRG in spinal cord injury (SCI) rats that exhibiting overactive bladder-like symptoms." (PMID 35077502, 2022). "We hypothesize that the TRPA1 in primary sensory neurons functions as a mechanical or nociceptive receptor and its activation may enhance afferent nerve activities induced by overactive bladder." (PMID 27315798, 2016). "Therefore the blockade of the TRPA1 channel may be a potential therapeutic target for bladder overactivity." (PMID 27315798, 2016). "TRPA1 up-regulation and TRPV1/TRPV4 down-regulation may account for the MGO-induced bladder overactivity." (PMID 32317986, 2020).
Sepsis (7 papers, 2019 to 2024). Sepsis is defined as life-threatening organ dysfunction caused by a dysregulated host response to infection. "Because TRPA1 is required to activate the homeostatic, protective reflex anti-inflammatory activity, we reasoned that TRPA1 deficiency renders animals more sensitive to sepsis." (PMID 36650454, 2023). "Further research is required to assess the potential importance of molecular pathways in vagal IL-1B/TRPA1 signaling and their combined role in immune regulation during sepsis." (PMID 38731999, 2024). "Their study revealed that mitochondrial biogenesis markers, including PGC-1α, NRF1, and TFAM, and mitochondrial fusion were decreased by TRPA1 blocker treatment in kidney tissues from either healthy or sepsis mouse." (PMID 37287081, 2023). "Mouse models of acute endotoxemia and sepsis were used to elucidate how specific activation, with optogenetics and chemogenetics, or ablation of TRPA1 neurons can affect the outcomes of inflammatory insults." (PMID 36650454, 2023). "In animal studies, TRPA1 prevented sepsis or IR renal injury by downregulating macrophage-mediated inflammation." (PMID 36875034, 2023). "The results of these experiments show that IL-1β stimulates TRPA1 afferent vagus nociceptors to activate an anti-inflammatory response which is protective against otherwise lethal cytokine-mediated inflammation and sepsis." (PMID 36650454, 2023). "In in vivo animal studies, TRPA1 prevented sepsis-induced or Ang-II-induced and ischemia-reperfusion renal injury by maintaining mitochondrial haemostasis or via the downregulation of macrophage-mediated inflammation, respectively." (PMID 33810314, 2021). "In vivo TRPA1 can prevent sepsis-induced renal injury by enhancing mitochondrial haemostasis and decreasing Ang II-induced or renal ischemia-reperfusion injury through the downregulation of macrophage-related inflammation." (PMID 33810314, 2021). "Additionally, it has been shown that TRPA1 can mediate sepsis-induced immunosuppression in response to IL-1B." (PMID 38731999, 2024). "The sepsis severity score in TRPA1 KO mice is significantly increased as compared to WT control mice for at least 6 days and moreover, mortality is increased significantly in TRPA1 KO mice as compared to WT (p < 0.05)." (PMID 36650454, 2023). "Moreover, TRPA1 protects the kidney from sepsis-related injury by promoting mitochondrial biosynthesis and homeostasis." (PMID 36875034, 2023). "However, two experimental animal studies suggested that TRPA1 protects against sepsis or angiotensin-II induced kidney injury." (PMID 31835897, 2019). "Another experimental animal study demonstrated TRPA1 may protect against sepsis-induced kidney injury by modulating mitochondrial biogenesis and mitophagy." (PMID 31835897, 2019).
acute kidney injury (6 papers, 2021 to 2024). Sudden and sustained deterioration of the kidney function characterized by decreased glomerular filtration rate, increased serum creatinine or oliguria. "A clinical observational study revealed that TRPA1 is upregulated in the renal tubules of patients with acute kidney injury (AKI), leading study authors to suggest that TRPA1 is associated with the progression of AKI to CKD." (PMID 34064835, 2021). "In renal failure, the role of TRPA1 in inflammation and injury suggests that it is involved in the mechanisms of kidney disease." (PMID 39273183, 2024). "Activation of TRPA1 increases intracellular calcium influx, while internalization of calcium crystals into renal tubular cells may lead to acute kidney injury." (PMID 37798747, 2023). "Acute kidney injury (AKI) patients with high renal tubular TRPA1 expression had low complete renal function recovery." (PMID 33810314, 2021).